NAMPT (nicotinamide phosphoribosyltransferase)
Diseases named in the same sentence as NAMPT in open-access papers (continued):
Sharing a sentence is not in itself a finding about the gene and the disease.
breast carcinoma (continued). "Their interconnection was shown experimentally on PHGDHhighMDA-MB-468 and PHGDHlow MDA-MB-231 breast cancer cells by treating them with well-established NAMPT inhibitor (FK866)." (PMID 30857125, 2019). "We also show, using both genetic and chemical inhibition, that NAMPT inhibition can increase the effect of olaparib in a number of tumour cell models for a disease of particular unmet therapeutic need, TN breast cancer." (PMID 22933245, 2012). "Further examination of NAMPT expression in breast cancer tissues through TIMER, TISIDB, and HPA databases demonstrated a positive association between NAMPT levels and macrophage immune enrichment, as well as a correlation with the M2 macrophage markers CD163 and CD206." (PMID 40083697, 2025). "Lastly, we demonstrate that the community cohesion scores can predict tamoxifen responses in ER+ breast cancer and suggest potential combination therapies (e.g. NAMPT and RXRA inhibitors) to reduce endocrine therapy resistance based on individualized characteristics." (PMID 38622359, 2024). "Likewise, in breast cancer, tumor-derived nicotinamide phosphoribosyltransferase (NAMPT) is involved in the generation of NAD+, thus supporting the NAD+-dependent deacetylation that regulates the transcription of lamin B receptor (LBR)." (PMID 38023616, 2023). "Moreover, NAMPT is a direct substrate of SIRT6 deacetylation, increasing NAMPT enzymatic activity in breast cancer 10.1096/fj.201800321R." (PMID 37491379, 2023). "Furthermore, there has been a recent report indicating a correlation between NAMPT activity and the characteristics of stemness in leukemia, glioma, colon cancer, and breast cancers." (PMID 38116009, 2023). "In breast cancer, NAMPT can facilitate tumor cell proliferation and invasiveness." (PMID 35515130, 2022). "The correlations between clinical pathologic variables and NAMPT levels in serum were reported in breast cancer patients, and the regulation regarding increased MDA-MB-231 cell invasion and migration was uncovered to be via the activation of c-Abl and STAT3 signaling." (PMID 35565188, 2022). "Furthermore, NAMPT has been found to induce breast cancer cell proliferation through the AKT/PI3K and ERK/MAPK signaling pathways, and to protect against apoptosis." (PMID 33912035, 2021). "Furthermore, NAMPT knockdown has been found to increase the aggressiveness of human breast cancer metastasis through the regulation of integrins." (PMID 33912035, 2021). "On the contrary, the transcription factor and tumor suppressor forkhead box O1 (Foxo1) binds to the 5′-flanking region of the NAMPT gene and downregulates NAMPT expression in breast cancer cells, an effect that is reversed by the insulin–PI3K–AKT signaling pathway." (PMID 34068917, 2021). "In this regard, SIRT6 mediates breast cancer cell cancer survival and oxidative stress resistance by regulating intracellular NAMPT activity and NAD(P)(H) levels, suggesting the use of SIRT6 inhibitors and agents inducing oxidative stress as a promising strategy for cancer treatment." (PMID 32488123, 2020). "Then, we investigated if the enhancement of miR-154 could reduce NAD levels and suppress breast cancer cell propagation via targeting NAMPT and whether this inhibition could modulate the cellular response to doxorubicin (DOX)." (PMID 31675930, 2019). "Accordingly, we aimed to investigate whether miR-381 up-regulation was associated with a significant decrease in NAD levels and, in turn, the suppression of breast cancer cells via targeting of the NAMPT 3′-UTR." (PMID 31611752, 2019). "Taken together, these results indicated that inhibition of NAMPT by miR-381 may have therapeutic potential for the treatment of breast cancer." (PMID 31611752, 2019). "The increased sensitivity of TN breast cancer cells to olaparid in presence of NAMPT inhibitor could be due most probably to the defect in homologous recombination genes (such as loss-of-function BRCA1 or BRCA2 mutations)." (PMID 31803365, 2019).
breast carcinoma (continued). "NAMPT is elevated in diverse human malignancies such as breast cancer." (PMID 31675930, 2019). "Here, the consequence of NAMPT inhibition by miR-154 was investigated on breast cancer cells." (PMID 31675930, 2019). "In breast cancer models, NAMPT increased the pool of NAD+ that could be converted to NADPH through the pentose phosphate pathway, thus maintaining glutathione in the reduced state." (PMID 32010616, 2019). "Therefore, the aim of this study was to assess the effect of NAMPT inhibition by miR-381 on breast cancer cell survival." (PMID 31611752, 2019). "For example, differential expression for the top GTs, nicotinamide phosphoribosyltransferase (NAMPT) was extracted from 30 abstracts and was found be to expressed in 20 cancers, such as ‘stomach cancer’, ‘breast cancer’, ‘endometrial cancer’, ‘b-cell lymphoma’ and ‘papillary thyroid carcinoma’." (PMID 29860481, 2018). "Furthermore, the increased levels of visfatin/NAMPT in breast cyst fluid show that induction of expression of NAMPT is not only a treatment of breast cancer tissue, but already characterized benign lesions, breast cysts." (PMID 27293305, 2016). "Furthermore, the N39 signature provides a potentially useful tool for prediction of recurrence-free survival in lung and breast cancer and validates NAMPT as a novel and effective therapeutic target in cancer." (PMID 25146220, 2014). "To further assess the generality of our observations, we addressed the possibility that NAMPT inhibition could also increase the therapeutic effect of olaparib in additional TN breast cancer cell lines." (PMID 22933245, 2012). "Elevated NAMPT expression levels were extensively reported in numerous solid and hematological malignancies, including pancreatic cancer, gastric cancer, prostate cancer, breast cancer, colorectal cancer, gliomas, ovarian cancer, melanoma, thyroid carcinoma, sarcomas, and lymphomas." (PMID 34068917, 2021). "In addition, the transcription of NAMPT gene can be directly regulated by FOXO1 in breast cancer." (PMID 31448236, 2019). "In the breast cancer study, the effect was noted to be greatest in BRCA-deficient models, suggesting that underlying defects in homologous recombination (HR) may further enhance the efficacy of NAMPT inhibition." (PMID 32010616, 2019). "In addition, adding a NAMPT inhibitor to ROS-containing plasma-activated medium resulted in increased ROS production, decreased intracellular reduced glutathione, and cell death of breast cancer cells." (PMID 32010616, 2019). "Therefore, supplementation with CA may aid suppression of the growth of breast carcinoma, which has higher NAMPT expression." (PMID 31817697, 2019). "Hence, it seems that inhibition of NAMPT could provide cutting-edge therapeutic strategies for breast cancer treatment." (PMID 31675930, 2019). "Therefore, it is possible that curcumin, in addition to inhibiting PHGDH directly by binding to its NAD+ pocket, hinders its activity indirectly by down-regulating expression of NAMPT (also known as visfatin) as has been demonstrated in breast cancer cell lines (MDA-MB-231, MDA-MB-468, and MCF-7)." (PMID 30857125, 2019). "Our proposed molecular signature that is composed of 39 NAMPT-mediated genes is a promising prognostic marker, because N39 was solely developed based on the discovery cohort and its prognostic power was validated in two independent validation cohorts for lung and breast cancer, respectively." (PMID 25146220, 2014). "Data from CPTAC database reveals that among breast cancer subtypes, TNBC tumors show a significant increase in NAMPT expression compared to normal breast samples." (PMID 41436543, 2025). "Recent studies have accentuated the potential benefits of combining NAMPT inhibitors and PARP1 inhibitors to enhance therapeutic outcomes, particularly in breast cancer." (PMID 38930900, 2024).
breast carcinoma (continued). "Nicotinamide phosphoribosyltransferase (NAMPT), the rate-limiting enzyme of the NAD+ salvage pathway is upregulated in various cancers, including gastric 4, colon 5, pancreatic 6, and breast cancers." (PMID 37771778, 2023). "In contrast, depletion, or inhibition of NAMPT resulted in antitumor effects by elevating levels of ROS in non-small cell lung cancer (NSCLC), glioblastoma, prostate cancer, breast cancer, and colon cancer." (PMID 38116009, 2023). "Reduction of NAMPT expression by knockdown led to a significant decrease in cell viability and concentration of NAD in breast cancer MDA-MB-231 cells." (PMID 35565188, 2022). "The overexpression of NAMPT could significantly enhance the abilities of invasion and migration in osteosarcoma and glioma cells; however, some studies draw the opposite conclusion that the knockdown of NAMPT promotes metastatic aggressiveness in breast cancer cells." (PMID 32005247, 2020). "Depletion or inhibition of NAMPT has been shown to increase ROS in models of NSCLC, leukemia, prostate cancer, breast cancer, glioblastoma, CRC, and others." (PMID 32010616, 2019). "The impact of H2S on NAMPT/SIRT1, likely, has global effects since it has been shown that RNA-mediated knockdown of NAMPT or NMNAT-1 in MCF-7 breast cancer cells reduced total cellular NAD+ levels and globally altered pattern of gene expression." (PMID 27732642, 2016). "ER-negative, basal-like breast cancers show increased expression of both PHGDH and nicotinamide phosphoribosyltransferase (NAMPT), the rate-limiting enzyme of NAD+ salvage, and are sensitive to NAMPT inhibition." (PMID 38698089, 2024). "Among which, SAA1, SAA2, HP, NAMPT, CHI3L1 and CHI3L2 have been reported to act as tumor promoters in multiple cancers including lung cancer, breast cancer and ovarian cancer." (PMID 38763993, 2024). "Furthermore, NAMPT/Visfatin altered the phenotypic properties of adipose-derived MSC and thereby promoted the malignant behaviors of breast cancer cells." (PMID 36750692, 2023). "Nicotinamide phosphoribosyltransferase (NAMPT), a critical enzyme for the NAD+ salvage pathway is reportedly overexpressed in numerous cancer types including breast cancer and treatment of cancer cells with the NAMPT inhibitor, FK866, is an active area of preclinical testing." (PMID 36067206, 2022). "Similar to NAMPT regulation, the RNA molecules miR-654-3p and the Down syndrome cell adhesion molecule antisense RNA 1 (DSCAM-AS1) were recently found to control the expression of QAPRT in ovarian and breast cancer cells, respectively." (PMID 34068917, 2021). "Our results revealed that negative-regulation of NAMPT by miR-381 induced apoptosis and decreased cell survival in breast cancer cells." (PMID 31611752, 2019). "Earlier, we had reported that inhibition of NAMPT by its specific inhibitor could effectively reduce NAD levels and induce apoptosis in breast cancer cells." (PMID 31675930, 2019). "Nicotinamide phosphoribosyltransferase (NAMPT), a rate-limiting enzyme involved in nicotinamide adenine dinucleotide (NAD) salvage pathway, is overexpressed in many human malignancies such as breast cancer." (PMID 31611752, 2019). "Similarly, data showing that both NAMPT overexpression and exogenous eNAMPT induced EMT in breast cancer cell lines, and that eNAMPT promoted osteosarcoma cell migration and invasion." (PMID 32010616, 2019). "Using an olaparib sensitization screen in a triple-negative (TN) breast cancer model, we identified nicotinamide phosphoribosyltransferase (NAMPT) as a non-redundant modifier of olaparib response." (PMID 22933245, 2012). "Studies conducted between 2018 and 2020 have shown that elevated levels of certain microRNAs (miR-381, miR-206, miR-494, miR-154, miR-23b, miR-26b) have a negative impact on the expression of NAMPT in breast cancer, pancreatic cancer, melanoma, and colorectal cancer." (PMID 37175631, 2023).
breast carcinoma (continued). "In addition, the analytical results of a cohort study indicated that the combination of the status of estrogen receptor-negative and high NAMPT levels in serum correlated with the poor disease-free survival in breast cancer." (PMID 35565188, 2022). "Breast cancer cell lines MDA-MB-468, MDA-MB-231, and MCF-7 showed the increased NAMPT expressions compared with the nontransformed MCF-10A cells." (PMID 35565188, 2022). "Importantly, the combination of a NAMPT small molecule inhibitor, FK866, with olaparib inhibited TN breast tumour growth in vivo to a greater extent than either single agent alone suggesting that assessing NAMPT/PARP inhibitor combinations for the treatment of TN breast cancer may be warranted." (PMID 22933245, 2012). "It should be noted, however, that in breast cancer cell lines, we have seen that KPT-8752 and KPT-9274 do block NAMPT activity, but that inhibition of NAMPT did not correlate with the ability of the compounds to block cell proliferation (Minden lab, unpublished results)." (PMID 28198380, 2017).
glioma (50 papers, 2011 to 2026). A benign or malignant brain and spinal cord tumor that arises from glial cells (astrocytes, oligodendrocytes, ependymal cells). "Elevated expression of NAMPT in glioma is associated with a cancer stem cell phenotype, increased tumourigenic properties and poor survival." (PMID 38893173, 2024). "Along with the reported overexpression of NAMPT in glioma cells, as well as its proposed association with oncogenic effects and poor prognosis in glioma, this made NAMPT an intriguing target." (PMID 35628596, 2022). "In conclusion, our data underline that targeting the NAMPT NAD+ regeneration pathway as a promising therapeutic option for gliomas with IDH1R132H mutation." (PMID 35628596, 2022). "NAMPT overexpression induced a transcriptomic signature that was associated with poor survival in human colon cancer or glioma tumors." (PMID 33384409, 2021). "Other examples include PTEN mutation in SW1783 cells associated with resistance to the NAMPT (nicotinamide phosphoribosyltransferase) inhibitor daporinad in EGFR amplified low-grade glioma cell lines." (PMID 33205120, 2020). "Recent work has demonstrated that N-MYC amplified gliomas, exerting dramatically increased dependence on glycolysis, may be particularly susceptible to NAMPT inhibition as an anti-metabolic therapy." (PMID 35814452, 2022). "To elucidate the causal role of NAMPT, we studied whether NAMPT promotes tumorigenicity in glioma cells." (PMID 29245920, 2017). "Importantly, the IDH1R132H mutation influenced the expression of the NAD-synthesis-associated enzyme NAMPT differently in the glioma cells and astrocytes, supporting the hypothesis that the IDH1 mutation differentially affects cells during tumorigenesis." (PMID 31888244, 2019). "Nicotinamide phosphoribosyltransferase (NAMPT) is the rate limiting enzyme in this salvage pathway, and its targeted inhibition caused NAD+ depletion and cell death in mIDH1 glioma cell lines." (PMID 39851960, 2025). "Alternatively, NAPRT silencing makes glioma cells reliant on the nicotinamide phosphoribosyl transferase (NAMPT)-dependent nicotinamide salvage pathway for NAD+ synthesis." (PMID 40565099, 2025). "NAMPT inhibition selectively kills mIDH1 tumor cells and induces tumor regression in orthotopic glioma xenografts." (PMID 40931345, 2025). "The results from animal studies in the orthotopic glioma model further confirm that NAMPT is an important functional target of PF403 to exert anti-tumor functions in vivo." (PMID 40486861, 2025). "In C6 glioma cells, inhibition of NAMPT using FK866 was able to reduce cell viability and block ERK/MAPK pathway activation resulting in G2/M cell cycle arrest and activation of autophagy." (PMID 38893173, 2024). "High levels of NAMPT, a rate-limiting enzyme in the salvage pathway, have been reported to induce tumor progression in various cancers such as glioma, melanoma, breast and colon cancers." (PMID 38625917, 2024). "Herein, we demonstrate that NAMPT is a biologically relevant cargo of MVs produced by NAMPT-overexpressing and radio-resistant GSCs and glioma cells." (PMID 37037593, 2023). "NAMPT expression levels negatively correlate with patient survival in a number of cancer types, including glioma." (PMID 37037593, 2023). "Oncometabolic rate assessment analysis showed significant increased ATP level (p<0.0001), NAD+ level [(NMNAT1 (p<0.0001), NMNAT3 (p<0.0001) and NAMPT (p<0.04)] and glutathione level (p<0.0001) in glioma patients compared to controls." (PMID 36809279, 2023). "High expression of NAMPT is characteristic of a huge range of solid and hematological NAMPT-dependent cancer, e.g., cancer of the stomach, pancreas, prostate, breast, ovary, melanoma, lymphoma, sarcoma, glioma, thyroid carcinoma." (PMID 37175631, 2023). "It was reported that NAMPT overexpression in glioma cell lines increases tumorigenic properties controlling stem cell pathways and enriching the cancer-initiating cell population." (PMID 36845744, 2023).